ATP5MF (ATP synthase membrane subunit f)
Description:
Subunit f, of the mitochondrial membrane ATP synthase complex (F(1)F(0) ATP synthase or Complex V) that produces ATP from ADP in the presence of a proton gradient across the membrane which is generated by electron transport complexes of the respiratory chain. ATP synthase complex consist of a soluble F(1) head domain - the catalytic core - and a membrane F(1) domain - the membrane proton channel. These two domains are linked by a central stalk rotating inside the F(1) region and a stationary peripheral stalk. During catalysis, ATP synthesis in the catalytic domain of F(1) is coupled via a rotary mechanism of the central stalk subunits to proton translocation (Probable). In vivo, can only synthesize ATP although its ATP hydrolase activity can be activated artificially in vitro (By similarity). Part of the complex F(0) domain.
Synonyms: ATP5J2; ATP5JL
Tractability: Small molecule: a structure with a bound ligand is known. Antibody: UniProt predicts a signal peptide or a membrane-spanning region.
Gene: Protein-coding gene on chromosome 7 (99,448,475 to 99,466,199, reverse strand). Ensembl gene ENSG00000241468.
Subcellular location: Mitochondrion; Mitochondrion inner membrane
Subcellular location (Human Protein Atlas): Mitochondria; Nuclear membrane
Pathways (Reactome):
Metabolism: Formation of ATP by chemiosmotic coupling
Organelle biogenesis and maintenance: Cristae formation
Gene Ontology:
Molecular function: proton-transporting ATP synthase activity, rotational mechanism
Biological process: proton motive force-driven mitochondrial ATP synthesis; proton motive force-driven ATP synthesis; proton transmembrane transport
Cellular component: mitochondrion; proton-transporting ATP synthase complex; mitochondrial inner membrane
Genetic constraint (gnomAD): Loss-of-function variants: 8 observed, 11.81 expected, observed/expected ratio (o/e) 0.68, 90% interval 0.4 to 1.22. The upper end of that interval is the gene's LOEUF score, 1.22, which puts it in group 5 of 6, group 1 being the genes least tolerant of losing a copy. Missense variants: 119 observed, 118.77 expected, observed/expected ratio (o/e) 1, 90% interval 0.86 to 1.17. Synonymous variants: 39 observed, 45.49 expected, observed/expected ratio (o/e) 0.86, 90% interval 0.66 to 1.12.
Homologues: Orthologues: chimpanzee ATP5MF (93% identical), dog ATP5J2 (77% identical), mouse Atp5mf (76% identical), Drosophila melanogaster ATPsynF (28% identical), Caenorhabditis elegans R53.4 (26% identical).
Diseases named in the same sentence as ATP5MF in open-access papers:
ATP5MF is named in the same sentence as 7 diseases in open-access papers, as found by Europe PMC text mining. Sharing a sentence is not in itself a finding about the gene and the disease. The quoted sentences say what the papers report.
tumor (3 papers, 2020 to 2024). "In addition, we found that many genes associated with ATP synthesis, such as ATP5F1D, ATP5ME, and ATP5MF, and genes associated with NADH oxidation, such as NDUFS8, NDUFB10, and NDUFC1, were overexpressed in LIHC and LUAD tumor tissues." (PMID 33262783, 2020).
ATP5MF also shares sentences with these, for which no sentence is quoted: adenoma (1 paper); Alzheimer disease (1); hematological disease (1); Huntington disease (1); neurological diseases (1); Parkinson disease (1).